MYCN (MYCN proto-oncogene, bHLH transcription factor)
Diseases named in the same sentence as MYCN in open-access papers (continued):
Sharing a sentence is not in itself a finding about the gene and the disease.
neuroblastoma (continued). "MYCN amplification is the most common genomic alteration in neuroblastoma, occurring in approximately 20% of the patients." (PMID 36353561, 2022). "As MYCN amplification closely correlates with the neoplastic prognosis of neuroblastoma, identifying MYCN amplification status is greatly important for related patients." (PMID 35820898, 2022). "This identification of potential lead natural compounds would be able to inhibit the Brd4 protein in neuroblastoma treatment by silencing the expression of MYCN." (PMID 36286044, 2022). "In neuroblastoma, gene amplification of the oncogenic transcription factor MYCN makes tumor cells more malignant and difficult to eliminate." (PMID 35530363, 2022). "Our findings identify cysteine uptake, transsulfuration and the lipid peroxidation-specific scavenging system as vulnerabilities in cancer cells driven by oncogenic MYC(N) activity such as MYCN-amplified neuroblastomas." (PMID 35484422, 2022). "These mice develop neuroblastoma tumors that molecularly and histologically resemble human tumors with MYCN amplification." (PMID 36077650, 2022). "Those genes were correlated with MYCN amplification and age at diagnosis of the neuroblastoma patients." (PMID 35764946, 2022). "MYCN genetic amplification occurs in 25% of neuroblastoma and is an unfavourable prognostic factor of neuroblastoma." (PMID 35655142, 2022). "More recent studies further confirm a critical role for MYCN in promoting glycolysis in neuroblastoma cells." (PMID 36077650, 2022). "In MYCN-amplified neuroblastoma lines, NCYM knockdown decreased levels of MYCN protein in a proteasome-dependent manner." (PMID 35451603, 2022). "Currently, the clinical outcome of NB is mainly predicted based on age, tumor stage, mitotic nuclear rupture index, MYCN (Neuroblastoma MYC Oncogene) amplification and ALK (Anaplastic Lymphoma Kinase) expression." (PMID 36430219, 2022). "We have previously shown that PI3K/mTOR inhibitors kill MYCN-amplified neuroblastoma cells and have the ability to eliminate MYCN protein in vivo." (PMID 34522028, 2022). "MDM2 overexpression maintains MYCN stabilization and translation in paediatric neuroblastoma cells and represents an unfavourable prognostic factor of neuroblastoma." (PMID 35655142, 2022). "These included the top MYCNARB1PRO downregulated TSTD1 and CDKN2C genes, which also showed a significantly lowered expression in MYCN-amplified compared with the MYCN-silent neuroblastomas." (PMID 36245757, 2022). "DHODH was identified to be an effective target in MYCN-amplified neuroblastoma cell lines and mouse neuroblastoma models." (PMID 35203388, 2022). "Pharmacological inhibition of both cystine uptake and transsulfuration combined with GPX4 inactivation resulted in tumor remission in an orthotopic MYCN-amplified neuroblastoma model." (PMID 35484422, 2022). "An in vitro study in neuroblastoma has shown interaction between miR-15a, miR‐15b and miR‐16 and MYCN transcript." (PMID 36348403, 2022). "Neuroblastoma and, in particular, MYCN amplified tumors are heavily dependent in glutamine, and blocking MYCN leads to the arrest of glutamine transport." (PMID 36139583, 2022). "In particular, it is thought to play a role in cancer development in MycN-amplified neuroblastoma IMR-32 cells." (PMID 35589670, 2022). "The oncogene MYCN was found to be amplified at extremely high levels in approximately 20% of neuroblastoma cases." (PMID 36438198, 2022). "In MYCN amplified neuroblastoma, glutamine deprivation induces the expression of pro‐apoptotic BCL2‐family proteins and subsequent cell death, dependent upon the transcription factor ATF4, the main effector of the Integrated Stress Response (ISR)." (PMID 36214609, 2022). "MYCN protein level is better than MYCN amplification status in predicting the prognosis of neuroblastoma patients." (PMID 35820898, 2022).
neuroblastoma (continued). "Today, diagnosis of neuroblastoma depends primarily on biopsy-dependent histopathology, which combined with genomic biomarkers (e.g., MYCN amplification) can provide information for staging and therapeutic intervention." (PMID 35957826, 2022). "Other data demonstrated a significant role of HDAC11 in mitotic cell cycle progression and survival of MYCN-amplified neuroblastoma cells and suggested that HDAC11 is potentially a valuable drug target." (PMID 35359455, 2022). "Non-MYCN amplified neuroblastoma cells (NBL-S, SH-SY5Y, and SK-N-AS) also responded to the presence of p110α inhibitors." (PMID 36585695, 2022). "The MYCN oncogene plays a major role in neural crest development and neuroblastoma tumorigenesis and defines an aggressive subset of tumors." (PMID 34716856, 2022). "In a panel of 32 neuroblastoma cell lines, MYCN or MYC amplification or translocation in adrenergic subtypes was accompanied by upregulated CBS expression, while MYC translocation/activation in mesenchymal cell lines was not." (PMID 35484422, 2022). "E2F transcription factors are involved in the development of neuroblastoma by regulating MYCN expression." (PMID 35764946, 2022). "More importantly, we also emphasized the critical role of BET inhibitors in combating neuroblastoma through regulating MYCN." (PMID 36187481, 2022). "For example, the abnormal activation of ERK1/2 signal in JQ1 resistant neuroblastoma cells attenuated the antitumor role of BET inhibitor by stabilizing MYCN protein." (PMID 36187481, 2022). "Consistently, knockdown of mouse Ezh2 by specific shRNAs led to a marked decrease in both MYCN protein levels and primary neuroblastoma cell growth." (PMID 35013218, 2022). "As MYCN-amplified and MYCN-driven neuroblastoma cell lines were very sensitive to the combination of verlindamycin and ATRA, we investigated the effect of this combined treatment on MYCN itself." (PMID 34522028, 2022). "Combinations of E2F1 expression, E2F3 expression with MYCN amplification or age of diagnosis achieved better prognosis of neuroblastoma." (PMID 35764946, 2022). "Numerous studies have shown that MYCN amplification correlates with neuroblastoma progressing rapidly, leading to a worse prognosis." (PMID 36171902, 2022). "Telomerase-mediated TMM in neuroblastoma can be determined by detecting the respective genomic alterations, i.e., amplification of MYCN (MNA) or rearrangements of TERT (TERT RA), or by examining TERT expression levels or telomerase activity." (PMID 36153564, 2022). "In a previous study on DNA methylation in neuroblastomas, methylation profiling reportedly distinguished samples with MYCN amplification." (PMID 36319669, 2022). "A recent report identified CaMKv as a potential immunotherapeutic target in MYCN-amplified neuroblastoma, due to its inordinately high expression in these tumors compared to normal human tissues." (PMID 35965782, 2022). "In vivo neuroblastoma cell proliferation and MYCN-mediated oncogenesis are both reduced in animal models when ODC is disabled." (PMID 36551330, 2022). "ALK, the second most common driver in neuroblastoma after MYCN, is a receptor tyrosine kinase which in the neuroblastoma context first attracted attention in conjunction with the rare hereditary neuroblastomas." (PMID 35362827, 2022). "Together, our results show that MYCN-amplified neuroblastomas increase transsulfuration activity, iron import, glutaminolysis and GSH production through coordinated changes in gene expression thereby increasing the susceptibility to ferroptosis." (PMID 35484422, 2022). "In neuroblastoma, abnormal expression of MYCN is the genetic aberration most consistent with treatment failure and poor prognosis." (PMID 36438198, 2022). "For instance, NK-derived exosomes carrying the tumor-suppressive miRNA-186 exhibited cytotoxicity against MYCN-amplified neuroblastoma cells, where miRNA-186 inhibited MYCN and exempted cancer cells from TGFβ1-dependent immune escape." (PMID 36119094, 2022).
neuroblastoma (continued). "For example, Lin28A/B was found to act as a post-translational driver of metastatic phenotype via direct enhancement of the translation of MYCN-induced transcripts in MYCN-amplified neuroblastoma." (PMID 36230562, 2022). "All patients presented with poorly differentiated neuroblastoma with segmental chromosomal aberrations; 4 patients also had tumors with confirmed MYCN amplification." (PMID 35089239, 2022). "Along the same lines, a more recent study showed that MYCN has a key role in maintaining cellular cysteine pools and that high MYCN expression sensitizes neuroblastoma cells to cystine deprivation, leading to lipid peroxidation and ferroptosis." (PMID 36077650, 2022). "We next evaluated the efficacy of MYCMI-7 in the MYCN-amplified SK-N-DZ neuroblastoma xenograft model in NMRI nu/nu mice." (PMID 36874405, 2022). "For example, in MYCN-amplified neuroblastoma, MYCN can bind to the promoter of telomerase catalytic subunit TERT, up-regulate and activate the expression of TERT which is a key function of amplified MYCN." (PMID 36187481, 2022). "It was reported that GAB2 plays important roles in neuroblastoma pathogenesis through promoting the cooperation of SHP2/MYCN." (PMID 35197367, 2022). "The selective effects of THZ1 on the proliferation and survival of MYCN-amplified neuroblastoma cells were observed in vitro and in vivo." (PMID 35681734, 2022). "A recent study in MYCN-amplified neuroblastoma showed that JQ1 and panobinostat commonly activate, and more often downregulate, target gene expression in MYCN-amplified neuroblastoma cells." (PMID 36357906, 2022). "We demonstrated that oncogenic MYCN sensitizes neuroblastoma cells to ferroptosis when intracellular cysteine availability for GSH synthesis and the cystine/cysteine redox cycle are limited." (PMID 35484422, 2022). "To further study the connection between MYCN levels and cell differentiation, we also investigated the effect of direct MYCN inhibition by siRNA on neuroblastoma cells." (PMID 34522028, 2022). "E2F1, E2F2 and E2F3 were shown to bind the promoter region and activate the transcription of the MYCN gene in MYCN-amplified neuroblastoma." (PMID 36479072, 2022). "This research focused on identifying potentially natural compounds that would be more patient-friendly, due to having fewer toxic effects and side effects, for treating MYCN overexpressing neuroblastoma patients by targeting the Brd4 protein." (PMID 36286044, 2022). "For instance, DDX21 was reported to induce CEP55 expression, MYCN-amplified neuroblastoma cell proliferation, and tumorigenesis." (PMID 35371306, 2022). "Here, the authors show that MYCN induces fatty acid uptake and synthesis to support neuroblastoma and inhibition of a fatty acid transporter impairs tumor progression in preclinical models." (PMID 35764645, 2022). "CCL2 and HLA class I genes were found more often downregulated in neuroblastoma tumors with MYCN amplification." (PMID 36923280, 2022). "MYCN amplification is the strongest predictor of high-risk neuroblastoma (NB)." (PMID 35681607, 2022). "In this review, we discuss the major metabolic pathways that are activated in neuroblastoma via transcriptional regulation, focusing on MYCN and pathway-specific transcription regulators in this metabolic rewiring process." (PMID 36077650, 2022). "Copy number variation studies uncovered an asymmetric pattern of amplification, according to which, the CRC-bound e4 enhancer is frequently identified in the majority of MYCN-amplified neuroblastomas examined." (PMID 36139535, 2022). "Together, these findings suggest that MYCN, ATF4, and KDM4C work together to promote glutamine uptake and metabolism in MYCN-amplified neuroblastoma cells to meet the biosynthetic demands of cell growth and proliferation." (PMID 36077650, 2022). "The in vivo potential of MYCMI-7 was investigated in three MYC-driven mouse tumor models: AML, breast cancer, and MYCN-amplified neuroblastoma." (PMID 36874405, 2022).
neuroblastoma (continued). "Previous data showed that Aurora kinase A (AURKA) interacted with both MYCN and FBW7α, and counteracted FBW7α-mediated MYCN degradation in neuroblastoma cells." (PMID 35013218, 2022). "This restricted expression pattern of MYCN observed in mice supports the clinical observation that neural tumors frequently overexpress MYCN, indicating that protooncogene MYCN plays an essential role in the development of children neuroblastoma." (PMID 35805002, 2022). "In the current study, by using in vitro models, we characterized human DC subsets migration and function in the context of neuroblastoma, with a special emphasis on MYCN-amplified tumor." (PMID 36923280, 2022). "MYCN amplification and age of diagnosis were critical determiners of the clinical outcomes of pediatric neuroblastoma." (PMID 35764946, 2022). "The endogenous expression of ALK and MYCN in these cell lines was also evaluated in our assay to confirm the different levels of the two genes in the selected neuroblastoma cell lines." (PMID 36585695, 2022). "Along with ODC, SAMDC is a target of MYCN and plays a significant role in the growth of neuroblastomas." (PMID 36551330, 2022). "Differential expression analysis verified a significantly higher expression of MYCN in the MYCN-amplified neuroblastomas." (PMID 36245757, 2022). "Patients are stratified into risk groups according to the International Neuroblastoma Risk Group (INRG) classification system, which includes patient age, tumor pathology, MYCN status, 11q status, and ploidy." (PMID 36029175, 2022). "The dysregulation of PI3K, HDACs, and MYCN are well known for promoting multiple cancer types, including neuroblastoma (NB)." (PMID 35205815, 2022). "Analysis of patient data reveals significantly higher ATF4 mRNA levels in neuroblastoma tumors with MYCN amplification and higher ATF4 expression is associated with poor prognosis in neuroblastoma patients." (PMID 36077650, 2022). "The effect of MYC family proteins on HLA generalizes to other cancers as well, as MYC and MYCN can suppress HLA-I in melanoma and neuroblastoma, respectively." (PMID 35775490, 2022). "A high MYCN state in neuroblastoma cells sensitizes them to lipid peroxidation, which in combination with acute intracellular cysteine reduction triggers massive ferroptotic cell death." (PMID 35484422, 2022). "While neuroblastoma is heterogeneous in cellular and transcriptomic states, amplification of the MYCN oncogene is one of the most significant biological features of high-risk neuroblastoma." (PMID 36612203, 2022). "Some miRNAs targeting MYCN, such as the let-7 family, work as inhibitors and are down-regulated in neuroblastoma, inducing N-Myc protein expression." (PMID 36139583, 2022). "MYCN transcriptionally upregulates the expression of MondoA (also known as MLXIP) in neuroblastoma cells, which is a member of the extended MYC network with a role in regulation of cellular metabolism." (PMID 36077650, 2022). "Previous results have shown that CCNE1 is a target of MYCN and an unfavourable prognostic marker of neuroblastoma." (PMID 35655142, 2022). "We then assessed the associations of age of diagnosis, MYCN amplification and E2F1 expression and E2F3 expression in the prediction of the overall survival of neuroblastoma using multivariable cox regression assay." (PMID 35764946, 2022). "Inhibition of MYCN function suppresses the proliferation and enhances the neuronal differentiation of MYCN-amplified neuroblastoma cells, and with different conditions, MYCN can either promote or inhibit apoptosis of neuroblastoma cells." (PMID 34625907, 2022).
neuroblastoma (continued). "The top score was obtained for AHR (Aryl Hydrocarbon Receptor) signaling pathway, which is inversely correlated to MYCN expression in neuroblastoma tissue." (PMID 36793342, 2022). "All these reactions in purine and pyrimidine nucleotide synthesis are catalyzed by glutamine amidotransferases (PPAT, PFAS, GMPS, CAD, and CTPS1/2), which are transcriptionally activated by MYCN in neuroblastoma cells." (PMID 36077650, 2022). "SK-N-AS is a non-MYCN amplified metastatic neuroblastoma cell line that endogenously expresses minimal levels of CD24." (PMID 36016357, 2022). "The expression levels of E2F1 and E2F3 were higher in neuroblastoma patients with MYCN amplification or age at diagnosis ≥ 18 months." (PMID 35764946, 2022). "Genomic knockout of SLC27A or pharmacological inhibition of SLC27A2 significantly attenuates the growth of MYCN-amplified neuroblastoma cell lines and tumors." (PMID 36077650, 2022). "The N-myc proto-oncogene (MYCN) is frequently amplified in neuroblastoma (around 20% of cases) and is one of the defining hallmarks of high-risk disease." (PMID 35943801, 2022). "MiRNAs targeting MYCN were found to be particularly important in regulating its expression in neuroblastoma in different ways." (PMID 36139583, 2022). "While MNA is considered a staple in neuroblastoma diagnosis MYCN over-expression has a more controversial role; in a similar manner, MYCN expression has the same prognostic behavior." (PMID 36139583, 2022). "We also showed that blocking a single cancer-specific gene (MYCN) is a more sustainable method for inhibiting the mTOR pathway in neuroblastoma cells only, avoiding side effects of mTOR inhibition in healthy cells." (PMID 35490242, 2022). "The regulatory role of the PI3K signaling pathway towards MYCN has been established in neuroblastoma previously, suggesting the PI3K signaling pathway as potential targets for neuroblastoma treatment." (PMID 36585695, 2022). "The 54 compounds were tested at 10 μM for their inhibition of the IMR32 human neuroblastoma cell line, in which the MYCN gene is amplified and actively expressed." (PMID 35269731, 2022). "In models of childhood neuroblastoma, expression of the MYCN oncogene in the developing neural crest drives tumorigenesis." (PMID 35972154, 2022). "CCNE1, SESN1, MYCN amplification and age at diagnosis were independent prognostic markers of neuroblastoma." (PMID 35655142, 2022). "Neuroblastoma with MYCN amplification are often characterized by a sparse and limited immune infiltrate in the tumor microenvironment (TME), and infiltrating immune cells lack activation markers." (PMID 36923280, 2022). "In neuroblastoma, MYCN amplification and 11q-deletion are important, although incomplete, markers of high-risk disease." (PMID 35859155, 2022). "Human MYCN is an oncogene involved in many tumors, including neuroblastoma, which is characterized as inappropriate proliferation of undifferentiated neuronal progenitor cells." (PMID 34625907, 2022). "In a previous article, we demonstrated that BGA002 was able to block MYCN expression in neuroblastoma cell lines." (PMID 35490242, 2022). "In the context of neuroblastoma, MYCN can modulate antigens expressed in tumor cells and thus influence immunosurveillance." (PMID 36923280, 2022). "All these data argue that the EZH2-MYCN axis sustains MYCN expression and amplifies MYCN-dependent oncogenic programs to promote neuroblastoma progression." (PMID 35013218, 2022). "These include increased dependencies on ISL1, GATA3, and MYCN in neuroblastoma, all of which were recently reported as part of the core regulatory circuitry (CRC) in neuroblastoma and associated with superenhancers." (PMID 35382456, 2022). "The modulation of the SLC3A2 polyamine exporter and other essential elements of the polyamine pathway in vitro is directly induced by MYCN, leading to increased polyamine production and accelerated neuroblastoma cell proliferation." (PMID 36551330, 2022).